ENSG00000308234 (novel transcript)
Gene: Long non-coding RNA gene on chromosome 6 (26,722,679 to 26,733,100, forward strand). Ensembl gene ENSG00000308234.
Gene Ontology:
Molecular function: triplet codon-amino acid adaptor activity
Biological process: translation